IGF1 (insulin like growth factor 1)
Diseases named in the same sentence as IGF1 in open-access papers (continued):
Sharing a sentence is not in itself a finding about the gene and the disease.
tumor (continued). "IGF-1 activates phosphoinositide 3-kinase (PI3K)/protein kinase B (Akt)/ mammalian target of rapamycin 1 (mTORC1) signaling pathways in cancerous cells to promote glycolysis and tumor cell proliferation, while simultaneously inhibiting apoptosis." (PMID 31293576, 2019). "In ID8hPON2 cells, the expression profile of many genes known to regulate tumor growth including BRCA1, cyclin and cyclin-dependent kinase 20, PTK2, Hypoxia-upregulated protein 1, p21-activated kinase 3, IL-18, IL-33, IGF-1, IGFBP2 and RNA-binding protein 9, were identified." (PMID 29531225, 2018). "In order to determine if targeting different components of the IGF-1/RhoA/ROCK crosstalk between BC cells and CAFs would affect primary tumor growth and metastasis, we treated MDA-MB-231 xenografts with the IGF-1R inhibitor PQ401, Y27632 or PQ401 combined with Y27632." (PMID 29535813, 2018). "Furthermore, increased levels of epidermal growth factor (EGF), insulin growth factor-1 (IGF1) and lysophophatidic acid (LPA) have been shown to promote tumor cell pro-migratory effects." (PMID 29416793, 2018). "Moreover, neutralization antibody against IGF1 significantly decreased the tumor growth promoting effect of ASC.B6, suggesting that IGF1 production contributed to the tumor growth-promoting effect of ASC.B6." (PMID 30185144, 2018). "On the contrary, in some studies, IGF1 mRNA expression was higher—but IGFBP3 mRNA expression was lower—when tumor tissues were compared to that of adjacent nontumor tissue." (PMID 29702590, 2018). "IGF-1 is a factor essential for cell growth, proliferation and differentiation and preclinical studies in NET cell lines have demonstrated that over-expression of IGF-1 and/or IGF-1R, can induce tumor cell proliferation and raise Chromogranin A (CgA) synthesis." (PMID 29854305, 2018). "IGFBP3 also displays intrinsic activity, independent of IGF1, and has been reported to be involved in tumor development and progression by regulating cell growth and apoptosis." (PMID 29947889, 2018). "Tumor characteristics such as tumor differentiation, multinodularity, distant metastasis, and tumor size seemed not to influence the release of IGF-1 in our cohort." (PMID 30064393, 2018). "Unlike IGF-1, IGF-2 is an epigenetically regulated gene mainly involved in fetal development and expressed by both alleles only in early tumor cells, which suggests that IGF-2 plays a critical role in oncogenesis." (PMID 30111747, 2018). "We found that IGF1-cultured tumor spheres appeared to initiate tumorigenesis with a significantly higher rate than their counterparts without IGF1 treatment (60% versus 20%), respectively." (PMID 30257507, 2018). "IGF-1 was shown localize to the cytoplasm of malignant tumour cells and surrounding stromal cells, while stronger cytoplasmic staining of IGF-1 was observed in the normal epithelial and stromal cells of adjacent non-tumourous tissue." (PMID 28143425, 2017). "Tumor tissue from mice treated exclusively with MSM exhibited reduced expression of IGF-1, STAT3, STAT5b, and VEGF without significant suppression of IGF-1R." (PMID 28300758, 2017). "Moreover, how IGF-1 and IGFBP-1 are regulated at the expression level remains equivocal in tumour tissues and within the circulating blood stream." (PMID 28143425, 2017). "However, insulin-like growth factor-1 (IGF-1) is considered as a HCC promoter since it can override homeostasis and lead to tumor progression during the initial steps of HCC development." (PMID 27713136, 2017). "However, the IGF-2/IR-A loop appears to be more important than the IGF-1/IGF-1R loop in thyroid cells with dedifferentiated and stem-like phenotype involved in tumor progression and metastasis." (PMID 29184536, 2017). "These endocrine disruptions led to an increase in circulating IGF-1, which can bind to the IGF receptor complex, and correspondingly activate pathways that stimulate cell proliferation and impair apoptosis, leading to tumor cell growth." (PMID 28336766, 2017).
tumor (continued). "The reduced expression of IGF-1R and VEGF may help prevent the development of tumors by reducing the insulin-like growth factor-1 (IGF-1)-mediated cell survival and proliferation pathways and preventing tumor-induced angiogenesis." (PMID 28300758, 2017). "Insulin and insulin-like growth factor (IGF)-1 have growth factor and antiapoptotic properties in a variety of cultured tumor and non-tumor cell types, including normal colon epithelium and colon cancer cells." (PMID 28060743, 2017). "Furthermore, IGF-1 expression was elevated in CD215+ myeloid cells and influenced tumor progression; additionally, its expression level was correlated with poor patient survival." (PMID 29255466, 2017). "In the absence of IGF1 administration, EphA4‐KO 4T1 tumor‐bearing mice showed significantly reduced tumor metastatic foci compared with that in control WT littermate mice." (PMID 26923183, 2016). "Several recent studies have shown that IGF-1 also induces EMT and favors the development of stemness features in various tumor cells, partly accounting for the migratory properties, invasiveness and resistance to conventional treatments reported in previous studies." (PMID 27764776, 2016). "The number of PBL significantly reduced in EphA4‐KO tumor‐bearing mice without IGF1 administration, but EphA4‐KO mice with IGF1 treatment showed an enhanced PBL number almost to the level of WT mice." (PMID 26923183, 2016). "All of the patients with persistently elevated IGF-1 continued to present GH suppression and 93% had no apparent tumor on MRI." (PMID 27982199, 2016). "At the same time in the analysis of 256 patients serum IGF-1 was not correlated with tumor stage or grade, but was independent favorable prognostic factors in a multivariable analysis." (PMID 27405474, 2016). "In the absence of IGF1 administration, the growth retardation of the primary tumor was observed in EphA4‐KO tumor‐bearing mice compared to that of control ‐WT tumor‐bearing littermate mice." (PMID 26923183, 2016). "Given that KRASG12D non-cell-autonomously regulates growth factor production from PSCs (e.g., IGF1 and GAS6), we hypothesized that KRASG12D-activated PSCs initiate a reciprocal signaling axis back in the tumor cells." (PMID 27087446, 2016). "We propose that tumor cells in CSF express IGF1R, but IGFBP3 prevents IGF1 from being bioavailable." (PMID 27255663, 2016). "Compared with either the spleen of tumor‐free mice or the spleen of EphA4‐KO tumor‐bearing mouse without IGF1 treatment, the splenic enlargement was conspicuous in the control EphA4‐WT tumor‐bearing mice." (PMID 26923183, 2016). "Although MK-0646 was the only treatment that failed to inhibit in vivo tumor growth, antibody efficacy was first confirmed as ‘IGF-1 Signaling’ was predicted as a significantly inhibited pathway in the MK-0646 cohort." (PMID 27765027, 2016). "Moreover, KRASG12D achieves a unique signaling output (e.g., production of ECM, IGF1, and GAS6) via stromal cells that is distinct from that produced by tumor cell KRASG12D alone." (PMID 27087446, 2016). "Myeloid cell precursors of EMH were very rare or markedly reduced in the liver of EphA4‐KO tumor‐bearing mice without IGF1 treatment, but markedly increased with IGF1 administration (F‐1, F‐2)." (PMID 26923183, 2016). "IGF1 treatment showed slightly increased IGF1 level in EphA4‐KO tumor‐bearing mice but the increase was not statistically significant." (PMID 26923183, 2016). "We also tested the effect of IGF1 treatment for the tumor metastasis of control WT tumor‐bearing mice, but the IGF1 treatment did not significantly further increase the metastatic foci (data not shown)." (PMID 26923183, 2016).
tumor (continued). "H&E and immunohistochemical staining for IGF-1 showed that treatment with AH6809/GW627368X did not alter the tumor types or IGF-1 expression." (PMID 25638159, 2015). "The potential mechanism could be through insulin growth factor-1 (IGF-1), where increasing energy could be responsible for glycemic overload and a compensatory increase of serum insulin and related IGF-1, a promoter of tumor cell growth in vitro." (PMID 25763533, 2015). "TRB3 expression in tumour nodules from TRB3 knockdown KK-Ay mice was much lower than that from control KK-Ay mice, suggesting that the higher insulin/IGF-1 in TRB3 knockdown KK-Ay mice cannot enhance TRB3 expression in the inoculated tumour cells as it does in the control KK-Ay mice." (PMID 26268733, 2015). "Furthermore, the addition of IGF-1 to the PLC/PRF/5 cell line induced increased cell proliferation in a dose dependent manner, showing that the major tumor promoting effects of IGF ligands on HCC are exerted through IGF-1R." (PMID 26329608, 2015). "In retrospective series response rate for K-RAS wild type patients showing HER-3 and IGF-1 negative tumours ranged in fact from 50 to 65%." (PMID 25943333, 2015). "Some tumours produce their own autocrine IGF1 (not insulin), most notably myeloma, but the majority of tumours do not, and thus are likely to depend on systemic levels for their growth." (PMID 26284118, 2015). "The IGF1/IGF1R axis is overexpressed and constitutively phosphorylated especially in PAX3/7-FOXO1 positive ARMS cells, this being one of the major tumorigenic pathways in this tumour." (PMID 26445453, 2015). "GALNT2 can modify IGF-1R O-glycosylation and interfere with IGF-1-triggered dimerization and activity of IGF-1R, thereby regulating downstream signaling events related to malignant properties of NB cells in vitro and tumor growth in vivo." (PMID 25362349, 2014). "Furthermore, together with tumor size, stage, and treatment response, IGF-1 levels were an independent predictor of poorer survival (for each 10 ng/mL decrease in IGF-1 level; HR, 1.057; 95% CI, 1.001–1.115; p = 0.045)." (PMID 24595361, 2014). "Of the five non-responders who had a ≥20 % decrease in tumor volume, three had decreases in GH and IGF-1 from core baseline." (PMID 23529827, 2014). "A key finding in this study was that higher IGF-1 expression in adjacent non-neoplastic liver than in tumor correlated with significantly poorer survival after resection of HCC." (PMID 25052889, 2014). "The relative expression of IGF-1 was significantly lower in tumor tissues as compared to paired non-tumor tissues (P<0.001)." (PMID 24586785, 2014). "With respect to tumor factors, IGF-1 levels as a continuous levels were not significantly correlated with maximum tumor size and serum α-fetoprotein (AFP) levels, but showed a negative correlation with tumor number (r = −0.206, P = 0.01)." (PMID 24595361, 2014). "Our results support the hypothesis that during hepatocarcinogenesis, secretion of IGF-1 by adjacent hepatocytes may lead to paracrine stimulation of HCC and more aggressive tumor behavior." (PMID 25052889, 2014). "In the multivariate analysis, IGF-1 levels, BCLC stage, larger tumor size, and mRECIST non-responders were independent risk factors for poorer OS." (PMID 24595361, 2014). "Additionally, the levels of IGF-1 showed a trend toward a decrease with advancingtumor stage, determined by the American Joint Committee on Cancer (AJCC) tumor-node-metastasis (TNM) staging (ρ = −0.218, P = 0.01) and Okuda (ρ = −0.273, P = 0.001)." (PMID 24595361, 2014). "Along the same line, some tumor cytokines, including Interleukin-1 beta, tumor necrosis factor-alpha and interleukin-6, were found to be elevated in HCC patients, have been reported to block IGF-1 production in the liver." (PMID 24586785, 2014).
tumor (continued). "The current evidence suggests that only a quarter of patients receiving SSA therapy for at least a year will not achieve any significant improvement in GH and/or IGF-1 levels or a reduction in tumor size." (PMID 24166706, 2014). "Even though most of the studies on PAPPA so far suggested its tumor-promoting role is largely IGF-1-dependent, anti-PAPPA therapy might provide therapeutic effects beyond the inhibition of the IGF-1/IGF-1R signaling axis." (PMID 23896451, 2013). "Together, these analyses again suggest that although the IGF-1 system clearly plays a role in ES tumor biology, neither high ligand availability nor high receptor number is consistently defined as a predominant driving factor for poor patient outcomes." (PMID 23431249, 2013). "High-dose TOR has been reported to compete with estrogen at the ligand-binding site of the ER, to suppress insulin-like growth factor-1-dependent growth and to have non-ER-dependent anti-tumor effects such as suppression of angiogenesis." (PMID 23679192, 2013). "In addition, αIR3 antibody, an IGF-1 mimetic, also induced IGF-1R down-regulation due to receptor internalization, which has been previously observed in tumor cells." (PMID 22879999, 2012). "By targeting the endothelial cell compartment, bevacizumab not only inhibits the supply of oxygen and nutrients to the tumor, but also interrupts the “paracrine effect” by inhibiting endothelial secretion of growth factors such as IGF1, bFGF, and HB-EGF, which can stimulate tumor proliferation." (PMID 22538017, 2012). "Additionally, qRT-PCR analysis indicated 13.17- and 2,28-fold up-regulation of IGF1 and its receptor (IGF1R) respectively in tumor tissues." (PMID 23285163, 2012). "This indicates that IGF-1 is a strong component of the CR effects in tumor growth, but is not sufficient for reversing all CR effects." (PMID 23342276, 2012). "Furthermore, the addition of both IGF-1 and IGF-2 to the PLC HCC cell line induced increased cell proliferation in a dose dependent manner, showing that the major tumor promoting effects of IGF ligands on HCC are exerted through IGF-1R." (PMID 21729319, 2011). "Several candidates could be considered, including for example, IGF-1, HGF and FGF, all of which favor tumor cell survival and proliferation." (PMID 21549007, 2011). "Studies using diabetic non-obese mice demonstrated the link betweendiabetes and tumor development and metastasis, which is dependent on insulin and insulingrowth factor-1 (IGF-1)." (PMID 23908801, 2011). "On the other hand, LIV-1 expression may also be stimulated by growth factors in the tumor microenvironment, since treatment with TGFα, TGF-β1, EGF, IGF-1 and β2-M all enhanced the LIV-1 level." (PMID 22110740, 2011). "Furthermore,network analysis showed that predictive genes are linked to the activity ofimportant secreted factors, which have the potential to influence tumor biology,such as IL1, IGF1, PDGF BB, AGT, and TGFβ." (PMID 21479216, 2011). "By contrast, the activation status of the IGF1-dependent signaling was not impaired in the skeletal muscle of tumor-bearing animals." (PMID 21048967, 2010). "Enhanced UPS-dependent protein breakdown has been associated with downregulation of the IGF1-dependent PI3K/Akt pathway, yet the latter is not reduced in the skeletal muscle of tumor-bearing animals." (PMID 21048967, 2010). "The ORs for a difference in IGF1 concentration between the highest and lowest fifth were 1·38 (95% CI 1·14–1·68) for oestrogen-receptor-positive tumours and 0·80 (0·57–1·13) for oestrogen-receptor-negative tumours (p for heterogeneity=0·007)." (PMID 20472501, 2010). "It was shown that almost half of the genes that affect tumor growth also affect the lifespan of animals that do not have tumors, indicating that the ability of the insulin/IGF-1 pathway to couple longevity and tumor resistance extends downstream of DAF-16." (PMID 21084729, 2010).
tumor (continued). "Unlike TGF-α, single or repeated applications of the tumor promoter TPA fails to alter IGF-1 expression." (PMID 21297902, 2010). "Identification of the pathways mediating the IGF1-Akt preservation of salivary function will allow specific targeting to the salivary glands without modifying tumor therapies." (PMID 19252741, 2009). "The IGF-1 signalling cascade is a well-established and ubiquitously expressed pro-survival pathway, and the IGF-1 receptor has been proposed to confer survival signals to a wide range of tumour cells." (PMID 19142186, 2009). "By linear regression model, we found IGF-1 levels may be related to preoperative CEA levels and tumour volumes with marginal statistical significance (P=0.07 and P=0.08, respectively)." (PMID 18781172, 2008). "The hepatic GH effector IGF-1 levels are not correspondingly increased in conditions with high endogenous plasma ghrelin levels, such as ghrelin-producing tumours." (PMID 18182992, 2008). "The activation of IGF1, BCL2 and CCND1 by PTGS2 might be the prolonged legacy of chronic inflammation in early stages of tumor generation." (PMID 17206280, 2007). "A favourable biochemical response, be it the achievement of a GH ≤ 2·5 μg/l and/or the normalization of IGF-1, at 12 weeks was not predictive of a significant reduction in tumour volume by the end of the study." (PMID 17465997, 2007). "Also, restriction of either diet significantly reduced the plasma levels of insulin-like growth factor-1 (IGF-1), a biomarker for angiogenesis and tumour progression." (PMID 14520474, 2003). "IGF-1 stimulates growth of new blood vessels in experimental systems and potentially SRIF analogues may inhibit tumour growth indirectly by decreasing IGF-1 production." (PMID 12085262, 2002). "Whether this reveals different effects of inhibiting CSF-1R compared with decreasing CSF-1 in the tumor, or whether the lack of IGF-1 upregulation reflects a limitation of our athymic model due to lack of T-cell signaling, remains to be investigated." (PMID 40844085, 2025). "Notably, concurrent inhibition of IGF-1/PI3K and CSF-1R using Linsitinib (OSI906) and Sotuletinib (BLZ945) has shown promising results, significantly extending median survival in preclinical models until tumor recurrence." (PMID 40427130, 2025). "Consequently, increased osteoclast activity releases matrix-embedded growth factors such as insulin-like growth factor 1 (IGF-1) and bone morphogenetic proteins (BMPs), which drive tumor growth and create a self-reinforcing cycle of bone degradation and metastatic advancement." (PMID 40426987, 2025). "Therefore, GHR expression, along with IGF1 and IGF1R levels, may provide a more comprehensive understanding of GH signaling in tumor progression." (PMID 40806252, 2025). "I consider radiotherapy as a third-line treatment for any symptomatic patient with persistently above normal IGF-1(≥1.5–2 ULN) on the maximum tolerated dose of first generation SSA (usually 40 mg octreotide or 120 mg lanerotide monthly) for at least 6 months and with unresectable residual tumor." (PMID 40575269, 2025). "This discrepancy suggests that while GH/IGF-1 excess may not consistently translate into a higher incidence signal at the population level, it could still play an important role in tumor biology and disease course." (PMID 41293738, 2025). "I consider using second-generation SSAs for any symptomatic patient with above normal IGF-1(≥1.5-2ULN) with unresectable residual tumor that does not respond to the maximum tolerated dose of SSA (usually 40 mg octreotide or 120 mg lanerotide monthly) for at least 6 months." (PMID 40575269, 2025). "Our observation that conditioned medium from IGF1-over-expressing CAFs robustly stimulated malignant phenotypes in CCA cells is consistent with the CAF heterogeneity map, which highlights growth factor-enriched iCAF subsets as key tumor promotors in intrahepatic CCA." (PMID 41275311, 2025).